CXCL1 (C-X-C motif chemokine ligand 1)
Diseases named in the same sentence as CXCL1 in open-access papers (continued):
Sharing a sentence is not in itself a finding about the gene and the disease.
lung adenocarcinoma (11 papers, 2016 to 2024). A carcinoma that arises from the lung and is characterized by the presence of malignant glandular epithelial cells. "CXCL1 also acts on endothelial cells, causing angiogenesis in lung adenocarcinoma and squamous cell carcinoma." (PMID 38673949, 2024). "High levels of CXCL8 (and CXCL1) in lung adenocarcinoma are linked to increased cancer risk and a poor disease prognosis, whereas low expression of CXCL1, CXCL7, and CXCL8 is associated with a better prognosis." (PMID 36164329, 2022). "Also, doses of ionizing radiation, such as 4 Gray (Gy) with radiation therapy, can cause an increase in CXCL1 expression in lung adenocarcinoma cells, which may contribute to treatment ineffectiveness." (PMID 38673949, 2024). "Analyses of TCGA data to correlate prognosis with cytokine mRNA expression in lung adenocarcinoma patients identified increased levels of the mRNAs for Csf3, Cxcl1, and IL-6 as significant indicators of a worse prognosis." (PMID 39338937, 2024). "Higher CXCL1 expression in NSCLC tumors, lung squamous cell carcinoma, and lung adenocarcinoma is associated with a worse prognosis for patients." (PMID 38673949, 2024). "When lung adenocarcinoma cells are exposed to a dose of 4 Gy of radiation, there is an activation of NF-κB and an increase in CXCL1 expression in these cells." (PMID 38673949, 2024). "The action of CXCL1 in lung adenocarcinoma tumors is regulated not only by changes in the expression of this chemokine but also by alterations in the function of its receptor, CXCR2." (PMID 38673949, 2024). "This means that a decrease in SETD2 expression in lung adenocarcinoma tumors leads to an increase in CXCL1 expression." (PMID 38673949, 2024). "Among the factors that reduce CXCL1 expression and function in lung adenocarcinoma cells, dachshund family transcription factor 1 (DACH1) can also be mentioned." (PMID 38673949, 2024). "Serum levels of CXCL1 are also increased in lung adenocarcinoma patients relative to healthy subjects, although another study shows that patients with early-stage NSCLC have lower levels of circulating CXCL1 than healthy subjects." (PMID 38673949, 2024). "CXCL1 expression occurs in lung adenocarcinoma cells and can be increased by interactions with other cells in the tumor niche, as shown by experiments on mouse cells." (PMID 38673949, 2024). "In comparison with adjacent lung tissues, the CXCL1 protein in lung adenocarcinoma was evidently elevated (P < 0.0001)." (PMID 31998654, 2019). "The production of large amounts of CXCL1 in a lung adenocarcinoma tumor leads to the recruitment of G-MDSC to the lymph node at an early stage of metastasis; these cells contribute to lymph node metastasis, which is related to the secretion of TGF-β1 by these cells." (PMID 38673949, 2024). "Second, SETD2 inhibits CXCL1 gene expression via catalyzing H3K36me3 formation within the promoter of CXCL1 and then indirectly influences related downstream signaling pathways to attenuate the proliferation of lung adenocarcinoma cells and the growth of tumors." (PMID 34715919, 2021). "Therefore, high CXCL1 expression in a tumor cell depends on the action of secretory factors such as basic fibroblast growth factor (bFGF) (lung adenocarcinoma and squamous cell carcinoma), IL-17 (lung adenocarcinoma and squamous cell carcinoma), VEGF (lung adenocarcinoma), and thrombin (NSCLC)." (PMID 38673949, 2024). "Considering the high protein abundance of CXCL1 in lung adenocarcinoma, we further analyzed the expression of CXCL1 in a TMA containing lung adenocarcinoma with matched adjacent lung tissue and clinicopathological parameters." (PMID 31998654, 2019). "We also found the substantial expression of several chemokines (CXCL1, CXCL5, CXCL8, and CX3CL1) related to cell migration, invasion, metastasis, or EMT, in KRAS-mutant lung adenocarcinoma cell lines, which was also dependent on MAPK signaling (unpublished data)." (PMID 27846317, 2016).
lung adenocarcinoma (continued). "Therefore, combined detection of CXCL1 and DACH1 could more precisely predict prognosis of lung adenocarcinoma." (PMID 31998654, 2019).
pneumococcal infection (11 papers, 2014 to 2024). Infections with bacteria of the species streptococcus pneumoniae. "In another study, pneumococcal infection was shown to trigger the release of IL-1β following the induction of CXCL1 and CXCL2 in epithelial cell." (PMID 38664730, 2024). "(2022) demonstrated that moderate alcohol consumption increased the expression of Cxcl1 in mice lung tissue during pneumococcal infection and was accompanied by the increase in neutrophil infiltrate." (PMID 37275853, 2023). "In conjunction with the increased production of NO in the BALF of ethanol-exposed mice during pneumococcal infection, we observed a significant increase in the amount of CXCL1 in the blood and BALF." (PMID 37275853, 2023). "The pneumococcal infection was also associated with a significant increase in the expression of IL-6, TNF-α, CXCL1, and IFNγ in both groups and was significantly higher in the Zip8KO group when compared to the WT animals (p = 0.055)." (PMID 35162945, 2022). "In a murine model of intrapulmonary Streptococcus pneumoniae infection, CXCL1 was found to enhance neutrophil influx to control bacterial dissemination in the lungs, resulting in improved host survival." (PMID 34439908, 2021). "The massive production of cytokines such as TNF-α, IL-6, IL-12, CXCL1, and CXCL2 was a hallmark of the secondary pneumococcal infection after the flu." (PMID 29326698, 2017). "The results showed that by 24 h after pneumococcal infection there was a significant increase of protein production of CXCL1, IL-6, TNF-α, CXCL10 and G-CSF in virus/S." (PMID 24408967, 2014). "Firstly, CXCL1 release, together with that of IL-1β and IL-6, plays a central role in Nφ mobilization from the bone marrow, in Nφ activation and in the control of bacterial dissemination in the lung after pneumococcal infection." (PMID 33042124, 2020). "Luminex-based analyses of pro- and anti-inflammatory cytokines showed significantly increased levels of CXCL1, CXCL2 and G-CSF in BALF of S100A9 KO mice as compared to WT mice on days 1 and 2 after pneumococcal infection." (PMID 37467233, 2023). "We subsequently measured G-CSF, CXCL1 and CXCL2 transcript levels in the lungs during high inoculum pneumococcal infection." (PMID 31776393, 2019).
bone cancer (10 papers, 2014 to 2026). A primary or metastatic malignant neoplasm affecting the bone or articular cartilage. "Fourth, spinal IL-17 neutralization was effective against CCI-caused neuropathic pain and bone cancer pain through decreasing CXCL1’s release." (PMID 36672133, 2023). "Research in a rat model of bone cancer pain revealed that liquiritin mitigates pain by impeding the spinal cord astrocyte CXCL1 and neuronal CXCR2 pathways." (PMID 39295943, 2024). "Pharmacological neutralization of IL-17 ameliorates chronic neuropathic pain and persistent bone cancer pain, as well as reducing spinal CXCL1 release." (PMID 36672133, 2023). "Strikingly, RvD2 treatment suppresses spinal IL-17 overexpression, chemokine CXCL1 release and astrocyte activation in mice undergoing sciatic nerve trauma and bone cancer." (PMID 36672133, 2023). "This study, for the first time, discovered that spinal IL-17 neutralization reduces CCI-induced neuropathic pain and sarcoma-induced bone cancer pain through the impairment of CXCL1’s release." (PMID 36672133, 2023). "In summary, the current findings identify an unrecognized pharmacological property of RvD2 in preventing and attenuating chronic neuropathic pain and bone cancer pain by spinal inhibition of IL-17 secretion, CXCL1 release and astrocyte activation." (PMID 36672133, 2023). "The spinal levels of IL-17, CXCL1 and GFAP were also measured to evaluate if these proinflammatory molecules were implicated in RvD2 anti-nociception in bone cancer pain." (PMID 36672133, 2023). "Collectively, these behavioral findings reveal the involvement of spinal IL-17 and CXCL1 signaling in the pathogenesis of persistent bone cancer pain and neuropathic pain." (PMID 36672133, 2023). "In contrast, NF-κB-mediated CXCL1 production was found to contribute to the maintenance of bone cancer pain, suggesting some regulatory relationship between NF-κB and CXCL1." (PMID 36434686, 2022). "Bone cancer-induced CXCL1 changes in the spinal cord are critical for the generation of BCP." (PMID 30606213, 2019). "In addition, CXCL1 seems to be crucial not only in neuropathic pain but also in inflammatory pain and bone cancer pain." (PMID 25789329, 2015). "Overall, these current findings identify that RvD2 therapy is effective against the initiation and persistence of long-lasting neuropathic pain and bone cancer pain, which may be through spinal down-modulation of IL-17 secretion, CXCL1 release and astrocyte activation." (PMID 36672133, 2023). "More strikingly, this is the first study in which pre-treatment with RvD2 downregulated spinal IL-17 secretion, CXCL1 release and astrocyte activation in both the CCI and bone cancer animals." (PMID 36672133, 2023).
cardiac hypertrophy (10 papers, 2021 to 2025). "In HF, neutrophils produce a large amount of C-X-C motif chemokine ligand 1 (CXCL1) to recruit circulating monocytes/macrophages to the myocardium and participate in the process of cardiac hypertrophy and dysfunction." (PMID 40520009, 2025). "For example, CXCL1 can induce angiotensin II and lead to myocardial hypertrophy, fibrosis and inflammation." (PMID 34976024, 2021). "In addition, the study pointed out that intervention with CXCL1 neutralizing antibody prevents the development of angiotensin II-induced cardiac hypertrophy, fibrosis, and inflammation." (PMID 40078458, 2025). "It is reported that CXCL1/CXCR2 axis mediates Ang II-induced cardiac hypertrophy and remodeling." (PMID 33869197, 2021). "Elevated CXCL1 is responsible for attracting CXCR2+ macrophages, leading to ventricular hypertrophy." (PMID 34385934, 2021). "UUO resulted in cardiac hypertrophy, accompanied by an elongation of the QRS wave on the ECG, decreased expression of Cxcl1, Cxcl9, and Il1b, reduced the number of CD11b+ cells, and increased in titin isoform parameters, such as T1/MHC and TT/MHC ratios, without changes in fibrosis markers." (PMID 40869420, 2025). "Thus, the interventions against CXCL1/CXCR2 may be effective for the prevention and treatment of UA-induced cardiac hypertrophy and inflammatory responses." (PMID 34385934, 2021).
Cerebral ischemia (10 papers, 2010 to 2025). Restriction of arterial blood supply to the brain associated with insufficient oxygenation to support the metabolic requirements of the tissue. "For example, CXCL1/GRO-α is upregulated in the early phases of cerebral ischemia, and promotes leukocyte migration to the inflamed tissue." (PMID 31923917, 2020). "In vivo, after cerebral ischemia, IL-1 production contributed to increased IL-6 and CXCL1 since these cytokines were profoundly reduced in the ischemic hemispheres from IL-1α/β double KO mice, although injury-induced cytokine responses were not abolished." (PMID 23024646, 2012). "The results of this study confirm previous findings from animal models and humans, that CXCL1 is increased in cerebral ischemia." (PMID 21124781, 2010). "Cerebral ischemia induced a transient increase of TNF, IL-1β, IL-6, CXCL1, and CCL5 at day 1 post-pMCAO, corresponding to the peak of pro-inflammatory cytokines typically observed in this model." (PMID 38142915, 2024).
emphysema (10 papers, 2011 to 2025). "When CXCL1 was blocked in PPE-induced emphysema mice, neutrophil migration into the lungs was markedly reduced, and the number of Siglec-F+ neutrophils was significantly decreased." (PMID 40461699, 2025). "Neutrophilic inflammation has been implicated in COPD pathology and in elastase-induced emphysema, and previous studies of allergic airways disease have linked DUOX1 to production of neutrophil chemokines (CXCL1) and neutrophil recruitment." (PMID 33301419, 2021). "We therefore turned to genes involved in neutrophil recruitment and looked at CXCL1, the transcripts of which are also selectively increased in emphysema dominant COPD." (PMID 34145303, 2021). "This may be associated with the granulocytosis discussed further below but may also relate to increased expression of proinflammatory cytokines Il1b and Cxcl1, and the emphysema-like pathology that develops in these animals." (PMID 39869647, 2025). "Importantly, we noted in male airway disease-dominant COPD an increased expression of macrophage associated genes, while in emphysema-dominant COPD neutrophil associated genes like CSF3R and CXCL1 were increased." (PMID 34145303, 2021). "In our study, one explanation for the mitigation of the emphysema was decreased levels of pro-inflammatory factors in the lungs (IL-1β and CXCL1/KC) and circulation (TNF-α, IL-1β, and IL-17A) by hUC-MSCs which may associate with the reduction of the neutrophil infiltration in emphysematous mice." (PMID 34646841, 2021). "Here both CXCL1 and MT-CO2 are induced by H2O2 suggesting that in male emphysema reactive oxygen may provide an important pathophysiological mechanism." (PMID 34145303, 2021). "However, we did not observe significant changes between WT and Duox1–/– mice with respect to overall neutrophil content during PPE-induced emphysema, based on intracellular MPO analysis, or with respect to induction of Cxcl1 mRNA." (PMID 33301419, 2021). "PM significantly increased mice emphysema and airway inflammation measured by mean linear intercept, alveolar destroy index and total cell, neutrophil counts, cytokines IL-6, tumor necrosis factor (TNF)-α, CXCL1, IL-1β in bronchoalveolar lavage fluid." (PMID 32116706, 2020).
fibrosis (10 papers, 2018 to 2025). the formation of excess fibrous connective tissue in an organ or tissue in a reparative or reactive process. "Beyond OSCC, CXCL1 expression has also been associated with stromal activation in oral potentially malignant disorders such as oral submucosal fibrosis and oral lichen planus (OLP)." (PMID 40490643, 2025). "In oral submucosal fibrosis, CXCL1 drives tumorigenic processes, including keratinocyte proliferation and migration, which contribute to the transition from oral submucosal fibrosis to head and neck cancer." (PMID 40490643, 2025). "On the other hand, it has been reported that rs4042 in the CXCL1 gene is related to the levels of some chemokines in the blood, which may suppress the progression of fibrosis in hepatitis C." (PMID 32570833, 2020). "In our study, we found that CXCL1 in activated HSCs was upregulated in CCl4-induced fibrosis." (PMID 29642635, 2018). "In CCl4-induced mouse fibrosis, GFAP-Cre;Bsgfl/fl mice showed less hepatic inflammatory infiltration and serum CXCL1 expression." (PMID 29642635, 2018).
inflammatory bowel disease (10 papers, 2015 to 2026). A spectrum of small and large bowel inflammatory diseases of unknown etiology. "CXCL1 causes chemotaxis and infiltration of inflammatory response sites by neutrophils in inflammatory bowel disease." (PMID 35806156, 2022). "For example, elevated expression of IL-17 and TNF-α in biopsies from colon mucosa of patients with inflammatory bowel disease showed elevated CXCL1 expression, dependent on the synergistic effects of those two cytokines." (PMID 35806156, 2022). "Neutrophils contribute to intestinal tissue damage in inflammatory bowel disease by producing ROS; CXCL1 also increases superoxide anion generation by these cells." (PMID 35806156, 2022). "In cases of inflammatory bowel diseases, the heightened expression of CXCL1 could potentially intensify disease progression and worsen symptoms by fostering the accumulation of inflammatory cells and promoting white blood cell adhesion." (PMID 40478904, 2025). "CXCL1 expression in normal mucosa is expressed mainly in crypts; however, in inflammatory bowel disease, CXCL1 expression occurs in pericrypt myofibroblasts, epithelial cells, enteroendocrine cells and in inflammatory cells such as macrophages and granulocytes." (PMID 35806156, 2022). "CXCL1 has important functions in the course of inflammatory bowel disease." (PMID 35806156, 2022). "During inflammatory bowel disease (IBD), inflammatory fibroblast subsets upregulate secretion of chemokines like IL-6, CXCL1, and CCL2, promoting neutrophil and macrophage infiltration." (PMID 41465375, 2025). "Elevated CXCL1 expression in the gut of patients with inflammatory bowel disease may also depend on other factors such as interferon-stimulated gene product 15 (ISG15)/ubiquitin cross-reactive protein (UCRP), IL-36α and IL-36γ, and the influence of gut microbiota." (PMID 35806156, 2022). "In the cellular model of inflammatory bowel diseases, ATF6 increases expression of inflammatory cytokines CXCL1 and tumor necrosis factor (TNF) in response to ER stress." (PMID 38007457, 2023). "CAR-Ms can also secrete CXCL1 and WNT, which coordinate the regeneration of damaged intestinal epithelial cells, offering a potential treatment for inflammatory bowel disease (IBD)." (PMID 39421021, 2024). "At the same time, CXCL1 is not the only neutrophil chemoattractant in inflammatory bowel disease." (PMID 35806156, 2022). "The inflammation and inflammatory bowel disease (IBD) disorders had many commonly modulated genes that were also found in the String analysis that were common with the disorders which included IL-8, ICAM1, RELB, NFκBIA, TNFAIP3, LIF, CXCL1, CXCL2, CXCL3, CXCL10, and TNF-α." (PMID 28099447, 2017).